CD28 (CD28 molecule)
Diseases named in the same sentence as CD28 in open-access papers (continued):
Sharing a sentence is not in itself a finding about the gene and the disease.
Autoimmunity (continued). "The CD28/CTLA-4 checkpoint is a critical arbiter of T cell activation and a hub of therapeutic intervention in both cancer and autoimmunity." (PMID 36347877, 2022). "TGN1412, a super-agonistic monoclonal antibody specific for CD28 (CD28SA) that is intended to activate Treg cells, was found to be therapeutically active in multiple rodent models of autoimmunity." (PMID 34708061, 2021). "Highlighting aspects of the immune imbalances and autoimmunity, the results of present study are a part of a discussion on the significance of CD3+CD8+CD28− cells in the pathogenesis of SLE." (PMID 27446964, 2016). "However, the persistent virus infection within the CNS in these CD28-deficient C57BL/6 mice does not lead to autoimmunity as seen in susceptible mouse strains such as SJL, leading to the conclusion that other factors besides virus persistence may contribute to this phenotype." (PMID 37090733, 2023). "In autoimmunity, CD4+ CD28- cells are expanded, but these were normally represented in our patient." (PMID 37371700, 2023). "Consistently, ablation of B7/CD28 signalling in CD80/CD86 knock-out mice or clinically with CTLA-4Ig (abatacept) has been shown to impair T cell regulation and lead to aggressive secondary autoimmunity." (PMID 32580776, 2020). "In all three cases depressed Treg numbers but lack of autoimmunity are coupled with a CD28 co-stimulation defect." (PMID 29479355, 2018). "The positive regulatory co-receptors CD28 and inducible co-stimulator (ICOS) transduce stimulatory co-signals, whereas the negative regulatory co-stimulators CTLA-4 and PD-1 are critical for the regulation of peripheral tolerance and autoimmunity." (PMID 28770269, 2018). "Other Foxp3− Treg cells include Tr1, Th3, CD8+CD28−/−, and Qa1-restricted T cells; however, the contribution of these Treg cells to self-tolerance, immune homeostasis as well as preventing autoimmunity is not well defined." (PMID 25152867, 2014). "Other Foxp3− suppressor T cells include Tr1, Th3, CD8+CD28−/−, and Qa1-restricted T cells; however, the contribution of these Treg cells to self-tolerance, immune homeostasis as well as preventing autoimmunity is not well defined." (PMID 25152867, 2014). "Therefore, in the context of autoimmunity, a potential drawback of CTLA-4 Ig is that although it may ameliorate inflammation by blocking CD28, it could also generate persistent, long-term memory Th17 cells by preventing exhaustion." (PMID 38226171, 2024). "We base this conclusion on transcriptome and proteome analysis of TNFR2- and CD28-costimulated CD4+ tTregs and conventional T cells (Tconvs), followed by bioinformatic comparison with published transcriptomic Treg signatures from NLT and LT in health and disease, including autoimmunity and cancer." (PMID 38341270, 2024). "The CD28 signal generated by the CD28 and CD80/CD86 interaction plays a critical role in T-cell activation and differentiation, and it has been demonstrated that the CD28 signal plays a key role in regulating immune tolerance and autoimmunity in animal models demonstrated in an animal model." (PMID 37457686, 2023). "In addition, our data showed that kallistatin did not activate the T cells of naïve mice by CD3/CD28 mAbs in vitro, suggesting that increased kallistatin helps to promote antigen-specific T cells during the development of autoimmunity." (PMID 34733288, 2021). "Thus, B7-CD28 co-stimulation determines the T cell repertoire through both thymic clonal deletion and Treg cell generation, with different CD28 signaling and B7-expressing APC requirements for these two cell fates to prevent destructive autoimmunity." (PMID 33293517, 2020). "One would have expected that T cell-mediated autoimmunity might involve aberrant expression of co-signaling receptors, with increased expression of co-stimulatory (e.g., CD28) and downregulation of co-inhibitory checkpoint (e.g., PD-1 and CTLA-4) molecules in autoimmunity." (PMID 29489833, 2018).
Autoimmunity (continued). "Consequently, it was conceivable that CD28 blockade by PV1 might increase Treg frequency and mitigate progression of autoimmunity in our uveitis model." (PMID 28248972, 2017). "However, the development of autoimmunity could not be observed in this C57BL/6 TMEV model irrespective of the time point of CD28 deletion." (PMID 37090733, 2023). "Thus, autoimmunity did not develop in the absence of CD28 in C57BL/6 mice, even when the virus could not be cleared similar to SJL mice." (PMID 37090733, 2023). "However, CD28 blockade alone is unlikely to be sufficient to prevent autoimmunity due to the fact that memory and CD8+ T cells are not as dependent as naïve CD4+ T cells on CD28 costimulation." (PMID 26783747, 2016).
rheumatoid arthritis (67 papers, 2004 to 2026). A chronic, systemic autoimmune disorder characterized by inflammation in the synovial membranes and articular surfaces. "The reduction in the expression of CD28 by T lymphocytes has been associated with a chronic state of immune system activation in rheumatoid arthritis." (PMID 38139422, 2023). "Recent genome-wide association studies (GWASs) identified CD28 as a susceptibility locus for lymphocyte and eosinophil counts, multiple sclerosis, ulcerative colitis, celiac disease, rheumatoid arthritis, asthma, and primary biliary cholangitis." (PMID 36271469, 2022). "The relationship between rs3116496 in CD28 and susceptibility to several diseases has already been evaluated, and significant associations have been found in type 1 diabetes, cervical and breast cancer, and rheumatoid arthritis." (PMID 27255376, 2016). "It has been reported that using CTLA-4 fusion protein to block the interaction between CD28 and B7 can inhibit the autoimmune response in experimental rheumatoid arthritis (RA)." (PMID 38524638, 2024). "Fine-mapping and functional studies implicate rs117701653, a non-coding single nucleotide polymorphism in the CD28/CTLA4/ICOS locus, as a risk variant for rheumatoid arthritis and type 1 diabetes." (PMID 38459032, 2024). "Enrichment of CD4+CD28− T cells in the inflamed tissue provided the first clue that patients with rheumatoid arthritis have premature immune aging." (PMID 35141865, 2022). "An increased number of premature senescent CD4+CD28- T lymphocytes has been frequently observed in osteolytic diseases, including rheumatoid arthritis, juvenile idiopathic arthritis, ankylosing spondylitis, osteopenia, osteoporosis, and osteomyelitis." (PMID 34341698, 2021). "In fact, finding an increased number of prematurely senescent CD4+CD28- T lymphocytes has become relatively common in rheumatoid arthritis, juvenile idiopathic arthritis, ankylosing spondylitis, osteopenia, osteoporosis, and osteomyelitis." (PMID 34341698, 2021). "The pathways common for tubular and glomerular DEGs were involved in immune response, with dendritic cell maturation, altered T cell and B cell signaling in rheumatoid arthritis, and CD28 signaling in T helper cells." (PMID 33644086, 2020). "Although previous experience with CD28 agonist mAbs has been disappointing, headway is being made in their use in solid tumors and rheumatoid arthritis." (PMID 31181772, 2019). "In rheumatoid arthritis patients, clinical response to abatacept, a CD80/86-CD28 T cell co-stimulation modulator, is associated with a concomitant decrease in CD8+CD28− T cells, suggesting prognostic value for this phenotype." (PMID 31181772, 2019). "Rheumatoid arthritis is associated with premature senescence of T-lymphocytes, and the accumulation of senescent CD4+CD28− T-cells has been linked with disease severity." (PMID 29472917, 2018). "In a TNFα-rich environment, such as in the case of rheumatoid arthritis, we found that anti-TNF therapy prevents the TNFα-induced loss of CD28 on the residual CD28+ CD8+ and CD4+ T cells, but the numbers of CD28null T cells remain the same." (PMID 27933066, 2016). "The decreased number of CD8+CD28− T-cells correlates with clinical response to abatacept in patients with rheumatoid arthritis." (PMID 27446964, 2016). "It has been shown that CD4+ T cells of rheumatoid arthritis patients express higher levels of CD28 and other markers of activated T cells than those of healthy controls." (PMID 24205378, 2013). "The blockade of CD28 co-stimulation by recombinant CTLA4IgG (abatacept) has demonstrated clinical utility in the treatment of rheumatoid arthritis." (PMID 22369699, 2012). "Inhibition of mitochondrial apoptotic cascade in CD4+CD28− T cells isolated from patients with rheumatoid arthritis has been shown to be the underlying molecular mechanism which gives rise to expansion and accumulation of CD4+CD28− T cells in these patients." (PMID 19779562, 2009).
rheumatoid arthritis (continued). "The high numbers of CD4+/CD28- T-cells found in patients with rheumatoid arthritis are consistent with this theory." (PMID 15613231, 2004). "Similar immune alterations have been described in systemic autoimmune diseases, including systemic lupus erythematosus and rheumatoid arthritis, where CD28 + granzyme K-high, perforin-low CD8 + T-cells infiltrate inflamed tissues and secrete proinflammatory cytokines such as IFN-γ." (PMID 41570020, 2026). "Recent genome-wide association studies (GWASs) identified CD28 as a susceptibility gene for various immunological diseases and traits, such as lymphocyte count, eosinophil count, multiple sclerosis (MS), ulcerative colitis (UC), celiac disease, rheumatoid arthritis (RA), and asthma." (PMID 36271469, 2022). "In rheumatoid arthritis patients, chronic exposure of total T cells to TNFα impairs cell-mediated immune responses via CD28 downregulation whereas memory CD4+CD45RO+ T cells acquire a stronger Th17 pathogenic profile compared to cells from healthy donors under Th17-polarizing conditions." (PMID 35216459, 2022). "Also, CD4+CD28- T lymphocytes isolated from the synovial fluid of rheumatoid arthritis-affected patients were capable of producing higher levels of IL-17A as compared with isolated CD4+CD28+ T lymphocytes." (PMID 34341698, 2021). "An updated CD28 superagonist TAB08 is under clinical testing for rheumatoid arthritis." (PMID 31181772, 2019). "In contrast to those isolated from healthy volunteers, CD4+CD28- T cells from rheumatoid arthritis patients may exhibit autoreactive properties." (PMID 25069714, 2014). "Interestingly, CD28+ CD27- TEMRA and EM CD4+ T cells expressing Th1- and cytotoxicity-associated genes have also been described to be increased and associated with higher damage in rheumatoid arthritis patients." (PMID 35185762, 2022). "Abatacept, an inhibitor of CD28 mediated T-cell activation, has been shown to be effective in controlling inflammation during rheumatoid arthritis (RA)." (PMID 33707483, 2021). "In rheumatoid arthritis, CD4+ Th cells play a pivotal role in the pathogenesis, as indicated by numerous genetic associations of the disease with polymorphisms in T cell related genes as well as by the clinical efficacy of CD28 co-stimulation and CD4 co-receptor blockade." (PMID 24667579, 2014). "Abatacept is the first in a class of agents for the treatment of rheumatoid arthritis (RA) that selectively modulates the CD80/CD86:CD28 co-stimulatory signal required for T-cell activation." (PMID 20398273, 2010). "The concept of interfering with T cell costimulation to treat autoimmune diseases has been clinically validated with abatacept (CTLA-4-Ig), an approved CD28 pathway inhibitor for rheumatoid arthritis (RA), juvenile idiopathic arthritis, and psoriatic arthritis." (PMID 34986869, 2022). "In contrast, a study in rheumatoid arthritis patients showed that tofacitinib inhibits the secretion of both IL-17 and IFN-γ in anti-CD3/anti-CD28 stimulated CD4+ T cells." (PMID 34020693, 2021). "Inflammatory microenvironment was created in vitro by the activation of T cells isolated from healthy donors and rheumatoid arthritis (RA) patients with anti-CD3 and anti-CD28 antibodies." (PMID 34863286, 2021). "We initially modulated CD28 costimulation by titrating abatacept (CTLA4-Ig), a drug used in treating immune diseases (e.g. rheumatoid arthritis) that reduces T-cell activation by blocking costimulation." (PMID 33223527, 2020). "They systematically examined 370 SNPs from 179 independent loci with P < 1 × 10− 3, and three gene regions in CD28, PRDM1 and CD2/CD58 were identified that were closely related to rheumatoid arthritis." (PMID 31842750, 2019). "In some connective tissue diseases, for example rheumatoid arthritis (RA), CD28− Treg-like cells revealed an increased number and abnormal cytokine secretion which might contribute to pathogenic immune response." (PMID 30479566, 2018).
rheumatoid arthritis (continued). "The biologic abatacept has traditionally been used for the treatment of rheumatoid arthritis (RA), where it acts as a T-cell inhibitor by binding to CD80 (B7-1) and CD86, thus blocking the costimulatory receptor CD28." (PMID 26490951, 2016). "Furthermore, in elderly individuals with chronic viral infections and autoimmune diseases (e.g., multiple sclerosis (MS), rheumatoid arthritis (RA), and Wegener's disease), an increase in the frequency of CD28− T cells has been detected." (PMID 24260712, 2013). "Thus, we obtained peripheral blood from healthy donors and rheumatoid arthritis patients, and CD4+ T lymphocytes were purified and cultured for 5 days in the presence of anti-CD3/CD28 beads and recombinant interleukin-2 (IL-2)." (PMID 36902005, 2023). "In contrast to rheumatoid arthritis, highly differentiated CD28− T cells did not accumulate in the blood or bone marrow of obese OA patients." (PMID 28615667, 2017). "Increased frequencies of CD28-negative CD4 and CD8 T cells expressing NK cell-associated receptors are a common finding in autoimmune diseases, in particular rheumatoid arthritis." (PMID 23761790, 2013). "Abatacept (ABA) is the first and only one of biological disease-modifying anti-rheumatic drugs (bDMARDs) for rheumatoid arthritis (RA) that inhibits T lymphocyte activation by binding to CD80/86, thereby modulating its interaction with CD28." (PMID 33184461, 2020). "In rheumatoid arthritis (RA) patients, culturing of CD4+CD28+ T cells with TNFα results in the reduction of CD28 expression on CD4 cells and generation of the CD4+CD28null subset by influencing CD28 gene transcription." (PMID 29546695, 2018). "Indeed, several studies reported an overall decrease in peripheral Tregs in kidney transplant recipients or rheumatoid arthritis patients treated with Nulojix® or Orencia®, which are CTLA4-Ig molecules binding CD80/86 and preventing CD28-mediated costimulation." (PMID 24376655, 2013). "The CD4+CD28- lymphocytes are suggested to acquire their phenotype in relation to increased proinflammatory state of the individual (notably increased levels of TNF), and themselves participate in inflammatory processes including rheumatoid arthritis, chronic kidney disease and atherogenesis." (PMID 23835405, 2013). "Several changes of the T-cell compartment have been described in rheumatoid arthritis (RA) patients, which include, in some patients, an increased number of T cells lacking the CD28 costimulatory molecule, which are clonally expanded." (PMID 25592982, 2015). "Patients with rheumatoid arthritis and JIA demonstrated increased CD28-negative T cells, an erosion of telomere length as a marker of replicative senescence and a loss of T cell receptor excision circles (TRECs) as a parameter of thymic function and peripheral proliferation of naive T cells." (PMID 24006909, 2013).
COVID-19 (51 papers, 2020 to 2026). A disease caused by infection with severe acute respiratory syndrome coronavirus 2. "We found an increased proportion of CD8 + CD28- TEMRA cells was independently associated with impaired COVID-19 vaccine antibody response." (PMID 36650551, 2023). "Nevertheless, the accumulation of CD28- senescent T cells has been associated with higher morbidity and mortality in COVID-19 patients." (PMID 38993862, 2023). "HLA-A*24:02-positive PBMCs from COVID-19 mRNA vaccine recipients were cultured with T cell activators (CD3/CD28/CD2) and IL-2 for 10 days to expand T cell populations." (PMID 41280906, 2025). "The immune profile of these patients was comparable to that of patients with severe COVID-19, and they had a significantly increased number of effector T cells and CD28- senescent T cells." (PMID 40002841, 2025). "On the other hand, the PD-1 pathway and CD28-mediated co-stimulatory pathway were negatively enriched in the low AUC group at T3, indicating a dysregulated T cell activation in the severe COVID-19 patients." (PMID 37918965, 2024). "Altogether, results of the unsupervised analysis suggested that COVID-19 correlated with a low expression of CD62L, CD28 and CD127, a hallmark of highly differentiated and short living effector cells (TEM or TEMRA)." (PMID 39136010, 2024). "In particular, the ICOS-ICOSL signaling in T helper cells, PKC signaling in T lymphocytes, T cell receptor signaling, calcium-induced T lymphocyte apoptosis, and CD28 signaling in T helper cells were all determined to be related to COVID-19 severity." (PMID 37308820, 2023). "EVs expressing T cell activation markers (CD154 and CD28) were higher in moderate and severe COVID-19 patients compared to the HCs." (PMID 36982991, 2023). "An impairment in T-lymphocyte function, with reduced capacity to produce IFN-γ and TNF-α upon stimulation with anti-CD3/anti-CD28 monoclonal antibody has been evidenced in COVID-19 patients." (PMID 35207531, 2022). "Lower circulating CD27+CD28+CD45RA+CCR7+ ‘naïve’ CD4+ T cell counts predicted a poor prognosis in patients with acute COVID-19." (PMID 35632823, 2022). "Monocytic cells isolated from PBMC of four severe COVID-19 patients exhibited suppressive activity on the proliferation of T cells stimulated with CD3/CD28 beads." (PMID 33692788, 2021). "A previous report indicated that SARS-CoV-2-reactive CD8+ T cells from convalescent patients with mild COVID-19 were predominantly TEMRA cells expressing CD28, suggesting a protective role." (PMID 35822004, 2021). "The comparison of cytokine concentrations in supernatants of PBMCs from COVID-19 patients vs. healthy subjects revealed lower concentrations of IL-10 and higher concentrations of IL-18 in supernatants of CD3/CD28-activated PBMCs from COVID-19 patients." (PMID 33634100, 2020). "Dental pulp stem cells exerted similar effects on the levels of IL-6 and GM-CSF in culture supernatants by resting vs. CD3/CD28-stimulated PBMCs from COVID-19 patients: up-regulation." (PMID 33634100, 2020). "Following PBMC activation with anti-CD3/CD28 antibodies, IL-10 showed lower levels, while IL-18 showed higher levels in supernatants of PBMCs from COVID-19 patients." (PMID 33634100, 2020). "On the other hand, we found that centenarians, COVID-19 patients, and cancer patients after treatment with platinum-based chemotherapy showed elevated frequencies of the terminally differentiated CD28− subpopulation within CD8+ T cells, compared to healthy individuals of similar age range." (PMID 40308557, 2025). "Given the increased arginase-1 expression, we went on to assess whether neutrophils from patients with COVID-19 possessed T cell–suppressive function by coculturing healthy anti-CD3ε– and anti-CD28–stimulated T cells with neutrophil supernatants." (PMID 39253969, 2024).